RAC1 (Rac family small GTPase 1)
Diseases named in the same sentence as RAC1 in open-access papers (continued):
Sharing a sentence is not in itself a finding about the gene and the disease.
breast carcinoma (continued). "The ectopic expression of miR-33b downregulated the expression of ADAM9, HMGA2, LDHA, SALL4, SNAI2 and Twist1 by more than 30% but had minimal effects on HIF-1α, RAC1, Yes1 and ZEB1 in these two breast cancer cell lines." (PMID 25919570, 2015). "We demonstrated that the migration and adhesion sequences of breast cancer cells, induced by SDF-1α gradients, involves successively the activation and inactivation of RhoA and an increased expression of Rac1 through the gradient." (PMID 26231656, 2015). "Beyond the importance of Rac1 in endothelial permeability and metastasis, Rac1 is aberrantly activated in a variety of tumors such as colon cancer, NSCLC, breast cancer, and generally plays an important role in cancer progression and metastasis." (PMID 25991673, 2015). "In breast cancer, the chemotactic and invasive activity of SDF-1α/CXCR4 is mediated by both Gα13-mediated activation of RhoA and Gαi-mediated activation of Rac1 via DOCK180/ELMO, which regulate cytoskeletal remodeling." (PMID 24887021, 2014). "These include p190RhoGAP, Rho, RAS, Rac1, Paxillin, p38MAPK, and ERK5 in breast cancer, and AKT, GSK3β, and βCatenin in esophageal cancer." (PMID 24788754, 2014). "Since Vav1 activates Rac1 in immune cells, we examined Rac1-GTP activation in the Vav1-expressing breast cancer cell lines." (PMID 23342133, 2013). "With Rac1-specific inhibitor, dominant negative mutant Rac1 (N17Rac1) and specific small interfering RNA, the effect of Rac1 on IR-induced G2/M checkpoint response and ERK1/2 activation was examined in human breast cancer cells." (PMID 22494620, 2012). "We report here that Rac1, stathmin, and EB1 were overexpressed in invasive breast cancer MDA-MB-231 cells compared to noninvasive breast cancer MCF7 cells." (PMID 21961005, 2011). "In summary, these data suggest that the mutations of CK1ε found in breast cancer can suppress Wnt/β-catenin as well as promote the Wnt/Rac-1/JNK and Wnt/NFAT pathways, thus contributing to breast cancer development via effects on cell adhesion and migration." (PMID 20507565, 2010). "Lack of CK1ε activity/expression leads to the activation of the Rac1/JNK/AP1 and NFAT pathways, which mediates the invasion of breast cancer cells and correlates with increased aggressiveness of the breast cancer." (PMID 20507565, 2010). "In the present study, we report that the expression of mevalonate pathway enzymes is mediated by the RHO guanosine nucleotide exchange factors VAV2 and VAV3 in a RAC1‐ and sterol regulatory element‐binding factor (SREBF)‐dependent manner in breast cancer cells." (PMID 39119789, 2025). "After Rac1 is activated, it mainly participates in EMT of breast cancer through PAK." (PMID 39673684, 2025). "Hence, BEC promote metastatic extravasation through activation of EGFR signalling in breast cancer cells that requires DOCK4, DOCK9, RAC1 and CDC42, rendering them competent for extravasation." (PMID 38762624, 2024). "The experiments showed that RAC1 is required for intercalation but not for adhesion of breast cancer cells onto BEC." (PMID 38762624, 2024). "In addition, multivariate analyses considered Rac1-GTP as an independent worse prognostic factor for both disease-free and breast cancer-specific survival." (PMID 39118792, 2024). "In addition to NSCLC, depleted levels of RAC1, CDC42, and RHOA were also observed in several other cell lines, including lung cancer (A549 and NCI-H1299) and breast cancer (MDA-MB-468 and MDA-MB-231), following PCAIs treatment." (PMID 38540084, 2024). "To assess whether Vangl regulates the cytoskeleton in leader cells, we employed time-lapse microscopy of collectively migrating breast cancer cells depleted of Vangl2 and stably expressing FRET biosensors for cytoskeletal regulators Rac1 and RhoA." (PMID 37147680, 2023).
breast carcinoma (continued). "In breast cancer cells, AXL promotes RAC1-dependent invasion through phosphorylation of ELMO68, a scaffold for DOCK family RAC GEFs, while in glioblastoma cells AXL-dependent invasion involves PI3K and RAC1 activity." (PMID 37322019, 2023). "Furthermore, both breast cancer cell lines exhibited significant reductions in the levels of KRAS, RHOA, RAC1, and CDC42 proteins of 49, 40, 50, and 48%, respectively in MDA-MB-468 cells." (PMID 36961909, 2023). "ITGB4 also promotes breast cancer cell resistance to tamoxifen-induced apoptosis by activating the PI3K/AKT signaling pathway and promotes breast cancer cell resistance to anoikis by activating RAC1." (PMID 37787041, 2023). "Furthermore, cucurbitacin B acts as a mediator in the distribution and reorganization of cytoskeletal proteins via RAC1/CDC42/RhoA signaling, altering the mechanical properties of MDA‐MB‐231 and SKBR‐3 breast cancer cells." (PMID 36585670, 2022). "MTSS1, a member of the IMD-family (IRSp53 and MIM (missing in metastasis) domain), serves as an actin-binding scaffold protein and stimulates the activation of Rac1-GTP, thus promoting cell–cell adhesions and preventing HER2+/ER−/PR− breast cancer cell migration and invasion." (PMID 35805075, 2022). "This pathway appears to be unique and distinct from the previously reported cortactin→Vav2→Rac3 cascade operating in invadopodia formed by breast cancer cells, in which Rac1 was not activated although it was substantially expressed." (PMID 34439396, 2021). "Clinically, RAC1 and BRD4 expression positively correlates in breast cancer patient's samples and show high expression patterns across different molecular subtypes of breast cancer." (PMID 34803511, 2021). "RAC1 and BRD4 showed high expression in different molecular subtypes of breast cancer and high expression of both proteins correlated with decrease survival of breast cancer patients." (PMID 34803511, 2021). "In addition, in breast cancer, TUFT1 promotes metastasis and chemoresistance through Rab5/Rac1 pathway." (PMID 34257606, 2021). "Both RAC1 and BRD4 proteins predict poor survival in breast cancer patients." (PMID 34803511, 2021). "Together, our data reveal the unacknowledged role of Rac1 in multiple chemoresistance of breast cancers by promoting the glycolysis in particularly non-oxidative PPP and nucleoside metabolism." (PMID 32193458, 2020). "Moreover, RAC1, CDC42, MYL9, MYLK, ABL1, and other genes have been proved to be related to the progress of human breast cancer." (PMID 33306680, 2020). "Moreover, the knockdown of Rac1 by siRNA in MCF-7 and MDA-MB-468 human breast cancer cell lines reduces EGF-induced cell migration and invasion." (PMID 32392742, 2020). "Silencing KRT19 resulted in decreased cell proliferation, migration, and survival, by decreasing the expression of PTEN through reduced expression of Egr1 and importin-7 and also regulated the nuclear import of β-catenin/RAC1 complex, thus modulating the NOTCH pathway in breast cancer." (PMID 33171868, 2020). "To examine whether the mRNA sequences of KRT19/RAC1 in colon cancer cells are different from those in breast cancer cells, we prepared RAC1 and KRT19 cDNA from colon and breast cancer cells." (PMID 30650643, 2019). "It is therefore interesting to investigate whether Rac1 and HIF-1α work as downstream effectors of SOX2 and NEDD9 in hypoxic breast cancer cells." (PMID 31462898, 2019). "ARHGEF16 (also known as Ephexin4, GEF16, or NBR) is a GEF that can activate RhoG, Rac1, and Cdc42 proteins of the Rho GTPase family and thereby promote migration and resistance to apoptosis of breast cancer cells independent of Ephrin signaling." (PMID 30305138, 2018). "To test these ideas, we compared the TGF-β1-arrested growth states of breast carcinoma cells and their presumed untransformed progenitors, the HMEC, and addressed the following issues: (i) Do Rac1 and Rac1b alter TGF-β1-induced cell migration and cell cycle arrest in breast carcinoma cells?" (PMID 28726720, 2017).
breast carcinoma (continued). "Further analysis is necessary to examine whether A77636′s action on Rac1 GTPase and/or RhoA GTPase may regulate matrix metalloproteinases such as MMP2 and MMP9 that may drive migration of breast cancer cells." (PMID 28374823, 2017). "In breast cancer cells, the Rac-GEF P-REX1 seems to be an essential mediator of RAC1 responses." (PMID 28499439, 2017). "This suggests that, unlike what occurs in MEFs, HER2-amplified breast cancer cells use Rictor within the context of catalytically active mTORC2 to downregulate RhoGDI2, allowing Rac1 activation and cell motility." (PMID 28666462, 2017). "Alternatively, as for Rac1, CDC42 may play a as yet to be determined role in the nucleus that is active in breast cancer cells." (PMID 28451966, 2017). "Besides activity in the receptor tyrosine kinase signal pathway, Rac1 promotes crosstalk with the Ras/Raf/MAPK pathway through ERK, which is an important serine/threonine kinase that inhibits breast cancer progression." (PMID 28549350, 2017). "Moreover, in breast cancer, HACE1 ubiquitinates and promotes the degradation of Rac1, then leading to impaired Rac signaling." (PMID 27213432, 2016). "We also found that the GEF TRIO and the GTPase RAC1 are potential downstream elements of ABL kinase negative regulation of invadopodia in TN breast cancer cells." (PMID 25803821, 2015). "Interestingly, PKCι is essential for K-Ras-driven invasion in colon cancer by regulating Rac1, while aPKCs mediates EGF-induced cell migration of MDA-MB-231 breast cancer cells." (PMID 24887021, 2014). "In breast carcinoma (MCF-7) cells stimulated with IL-1β, lipid rafts containing Vav1 and Rac1 could be detected." (PMID 24877606, 2014). "Although not mutually exclusive, a second possibility that may account for the BCAR3-dependent Rac1 activity observed in invasive breast cancer cells is that BCAR3 may actively suppress RhoA signaling, leading indirectly to Rac1 activation." (PMID 23762409, 2013). "It is conceivable that disruption of the feedback loop between Rac1 and E-cadherin adherens junctions could lead to aberrant STAT3 activation in breast cancer." (PMID 22689141, 2012). "Our findings show that CK1ε has the potential to act as a tumor suppressor in breast cancer via its negative effects on the Wnt/Rac1/JNK and NFAT pathways." (PMID 20507565, 2010). "Furthermore, in this study, the primary Rac effector of neuroblastoma appeared to be Rac2, as opposed to Rac1 in melanoma, prostate cancer, breast cancer, and liver cancer." (PMID 38884093, 2024). "In addition, several researchers reported that elevated levels of Rac1 could be activated by the upstream modulator of PI3K/AKT in gallbladder carcinoma, gastric cancer, and breast cancer." (PMID 35953862, 2022). "In a highly metastatic breast cancer cell line (MDA-MB-231BO), osthole downregulated the expression of integrin α3 and integrin β5, which was upregulated in highly metastatic breast cancer, and attenuated cell migration and invasion possibly via suppression of focal adhesion kinase/Src/Rac1." (PMID 36160431, 2022). "Altogether, this data suggests that the activation of Rac1 and Cdc42 is critical for breast cancer extravasation and metastatic colonization, and that ZINC69391 may provide a promising therapeutic option for aggressive breast cancer." (PMID 32992837, 2020). "Therefore, inhibiting P-Rex may block breast cancer metastasis, and the compound 1A-116, an analog of the previously discussed ZINC69391, was shown to inhibit the interaction of the GEF P-Rex1 with Rac1 with an IC50 = 4 μM." (PMID 32322580, 2020).
breast carcinoma (continued). "Furthermore, breast cancer cells treated with GA acquired a non-migratory phenotype and the changes in the cytoskeleton of these cells resembled those observed in cells when RAC1 signalling was abrogated." (PMID 31578236, 2019). "Additionally, we checked transcription levels of RAC1 in breast and colon cancer cells and revealed that the mRNA level of RAC1 did not change in colon cancer cells, whereas RAC1 mRNA levels were significantly downregulated in breast cancer cells." (PMID 30650643, 2019). "The expression of GFP–SUMO1–RAC1 but not that of wild-type RAC1 re-established the invasive capacity of these breast cancer cells upon exposure to GA, as well as their migratory phenotype as assessed by the capacity to form lamellipodia and ruffled structures in the proximity of the plasma membrane." (PMID 31578236, 2019). "RAC1, but not RAC2 or RAC3 genes, contains an additional exon 3b that is included by alternative splicing in the variant of RAC1b, a constitutively active mutant that is expressed primarily in colon and breast cancer." (PMID 31027363, 2019). "Considering that ARHGAP15 suppresses breast cancer cell proliferation and migration it may be possible to speculate that anti-tumorigenic effects of androgens are partially due to the induction of ARHGAP15 and subsequent inactivation of Rac1." (PMID 29534468, 2018). "However, in breast cancer, prostate cancer, pancreatic cancer, gastric cancer, as well as in NSCLC cell lines, miR-146a-5p acted as a tumor suppressor through the targeting of Rac1/ROCK1/EGFR." (PMID 27494902, 2016). "Given our findings that Rictor/mTORC2 is required in the normal mammary epithelium for PKC-alpha-Rac1 activation which drives MEC survival, motility, and invasion, it will be interesting to determine if the mTORC2-PKC-alpha-Rac signaling axis is used by breast cancer cells to drive metastasis." (PMID 26132202, 2015). "Thus, it is worthwhile to explore whether PI3K and ERK signaling pathways are involved in hypoxia-induced Rac1 activation and HIF-1α induction in breast cancer cells." (PMID 21980400, 2011). "Thus, using the cBioPortal database, we asked whether the negative correlation between ZNF750 and RAC1 observed in breast cancer cell lines was also conserved in human breast cancer by using publicly available breast cancer datasets." (PMID 33298895, 2020). "When we associated Rac1 immunoreactivity with disease-free survival and breast-cancer-specific survival, we could not detect any statistically significant difference between Rac1-positive and Rac1-negative cases (p = 0.42 for disease-free survival and p = 0.18 for breast-cancer-specific survival)." (PMID 29534468, 2018). "As direct interaction between Rac1 and Pak1 or WAVE2 is not detected in breast cancer cells, it is reasonable to assume that βPIX, the Pak-interacting nucleotide exchange factor of Rac/Cdc42, plays an important role in the signal transduction between Rac1 and Pak1." (PMID 22315597, 2012). "Therefore, it may be reasonable that hypoxia-stimulated ROS generation in breast cancer cell line MCF-7 is independent of Rac1 activation." (PMID 21980400, 2011). "Additionally, the expression and activity of NaV1.5 and Rac1 may be regulated differently at various stages of disease progression, meaning that studies at a single time point may not capture their dynamic changes throughout breast cancer progression." (PMID 39673684, 2025). "BEC-conditioned media promote EGFR activation, breast cancer cell elongated morphology and filopodial protrusions; and knockdown of either DOCK4 or RAC1 reverses cancer cell elongation without affecting filopodia." (PMID 38762624, 2024). "Although this model accurately reproduces the typical polarized ruffling dynamics, as observed in breast cancer cells (MDA-MB-231), it only reproduces simultaneous but not the delayed activation of Rac1 and Cdc42." (PMID 37371108, 2023).
breast carcinoma (continued). "We and others have reported that RAC1 signaling potentiates the TSH-induced transcription of the NIS (SLC5A5) gene in non-transformed thyroid cells, and also in MCF7 breast cancer cells, in this case through the activation of p38 MAPK signaling." (PMID 34771624, 2021). "This would indeed fit with our observation that β2-chimaerin overexpression failed to reduce Rac1-GTP levels in both DU145 and PC3 prostate cancer cells while still achieving a reduction in MCF-7 breast cancer cells." (PMID 32092966, 2020). "Knockdown of Rac3, but not of Rac1 or Rac2, induces autophagy in different tumor cell lines, including prostate cancer PC3 and breast cancer MDA-MB-231 cells that express low levels of Rac3." (PMID 31514269, 2019). "This is in agreement with previous reports showing a link between ABL kinases and TRIO or RAC1 and with a recent study demonstrating a negative regulatory role of the TRIO-RAC1 axis on invadopodia activity of breast carcinoma cells." (PMID 25803821, 2015). "In noninvasive breast cancer MCF7 cells, no lamellipodia were induced by IGF-I, whereas in MDA-MB-231 cells, Rac1, stathmin, and EB1 were overexpressed." (PMID 21961005, 2011). "In addition, Rho GTPases regulate many pathways important in the malignant phenotype, and CDC42 activity (but not RhoA or Rac1) is required for TEM and metastatic progression in prostate and breast cancer models." (PMID 34374417, 2021). "Here, the authors show that Rac1 increases glycolysis and non-oxidative pentose phosphate pathway activity leading to neoadjuvant chemotherapy (NAC) resistance, thus its inhibition sensitizes resistant breast cancer PDXs to NAC." (PMID 32193458, 2020). "In this paper, the results showed that DAPT activated Cdc42 but not Rac1, implying that modulation by Cdc42 on F-actin polymerization may be the reason for reduced migration in DAPT treated breast cancer cells." (PMID 31057403, 2019). "Although direct interaction between Rac1 and WAVE2 is not detected in human breast cancer cells, Rac1 forms a complex with CLIP-170, a microtubule-binding protein, an actin cross-linking protein IQGAP1, and kinesin-1, one of the major motor proteins, under the growth-arrested conditions." (PMID 22315597, 2012). "Interestingly, we failed to observe any changes in HIF-1α mRNA transcript levels for Rac1 transfectants, indicating that Rac-induced HIF-1α expression in breast cancer cells is independent of mRNA regulation." (PMID 21980400, 2011). "However, our study showed that Rac1 expression did not correlate to lymph node or distant metastasis in breast cancer, implying the shorter DFS in Rac1 overexpressed breast cancers might be due to the resistance to chemotherapies." (PMID 32193458, 2020).